Y_RNA (Y RNA )
Gene: Miscellaneous RNA gene on chromosome 10 (74,551,392 to 74,551,493, forward strand). Ensembl gene ENSG00000206756.
Homologues: Orthologues: macaque Y_RNA (99% identical), chimpanzee Y_RNA (97% identical), tropical clawed frog Y_RNA (78% identical). Paralogues in human: Y_RNA (93% identical), RNY3 (91% identical), Y_RNA (91% identical), RNY3P1 (89% identical), RNY3P4 (89% identical), Y_RNA (89% identical), Y_RNA (88% identical), RNY3P2 (87% identical), Y_RNA (87% identical), RNY3P14 (86% identical), Y_RNA (86% identical), RNY3P16 (85% identical), and 97 more.